HIF1A (hypoxia inducible factor 1 subunit alpha)
Diseases named in the same sentence as HIF1A in open-access papers (continued):
Sharing a sentence is not in itself a finding about the gene and the disease.
diabetic eye disease (2 papers, 2014 to 2023). A group of disorders affecting the eye in patients with diabetes mellitus. "Moreover, HIF-1α played important roles in some diseases under hypertonic condition, such as diabetic eye disease and some renal diseases." (PMID 25050781, 2014). "Intraocular administration of a single dose of 32-134D inhibited HIF-1α and HIF-2α protein accumulation, thereby normalizing the expression of HIF-regulated vasoactive genes in mouse models of diabetic eye disease." (PMID 37227777, 2023).
eosinophilia (2 papers, 2013 to 2022). "Blockade of HIF-1α in vivo, significantly decreased allergic inflammation and eosinophilia induced by allergen, due to a reduction in the levels of IL-5 and Eotaxin-2." (PMID 23935964, 2013). "Moreover, treatment with HIF-1α antagonist YC-1 can decrease airway hyper-responsiveness, blood eosinophilia, and allergic inflammatory gene expression in asthmatic mice." (PMID 36676950, 2022). "Interestingly, previous studies have shown that heterozygous-null mice in HIF-1α are protected from lung eosinophilia." (PMID 23935964, 2013).
ependymoma (2 papers, 2010 to 2025). A WHO grade II, slow growing tumor of children and young adults, usually located intraventricularly. "Four out of the five ependymomas with perinecrotic HIF‐1α expression showed moderate (++) expression of KIT in tumor endothelial cells." (PMID 20030644, 2010). "Five ependymomas contained tumor necrosis, and HIF‐1α was present in the perinecrotic tumor cells at a faint or moderate intensity in all these tumors." (PMID 20030644, 2010).
germ cell tumor (2 papers, 2021 to 2023). A benign or malignant, gonadal or extragonadal neoplasm that originates from germ cells. "We recently demonstrated that neuritogenesis-related protein neuritin 1 (NRN1) can be a potential therapeutic target in testicular germ cell tumor (TGCT) under the regulation by HIF1α." (PMID 34804954, 2021). "We have previously showed that NRN1 is abundantly expressed in testicular germ cell tumor PDC spheroid culture, and NRN1 expression is transcriptionally regulated by hypoxia inducible factor 1α (HIF1α)." (PMID 34804954, 2021). "Moreover, hypoxemia-induced factor 1-a (HIF-1a) is also affected by vitamin D, which plays a role in epithelial–mesenchymal transmission, migrations and has an impact on vascular proliferation; however, no study addressing the role of vitamin D and HIF-1a in germ cell tumors currently exists." (PMID 37114140, 2023).
glottis carcinoma (2 papers, 2012 to 2019). A carcinoma that arises from epithelial cells of the glottis. "In a study on the radiotherapeutic effect on early-stage glottic carcinoma, HIF-1α overexpression was closely correlated with the worse local control of tumor in the early-stage glottis carcinoma after radiotherapy." (PMID 23762617, 2012).
hemochromatosis (2 papers, 2021 to 2024). A disorder of iron metabolism characterized by a triad of HEMOSIDEROSIS; LIVER CIRRHOSIS; and DIABETES MELLITUS. "To investigate the role of the two HIF1A variants on HAMP activity, we performed in vitro experiments on Huh-7, a human hemochromatosis cell line." (PMID 33513852, 2021). "To confirm this finding, we analyzed hepcidin levels in the plasma of 6 patients affected by hemochromatosis, 3 of them homozygous for HFE-p.C282Y and 3 homozygous for HFE-p.C282Y and heterozygous for HIF1A-p.P582S." (PMID 38244120, 2024).
Hereditary breast cancer (2 papers, 2018 to 2021). Breast carcinoma that has developed in relatives of patients with history of breast carcinoma. "Increase in VEGF and HIF1α expression has been observed in BRCA1/2-related and hereditary breast cancer when compared to sporadic breast cancer as well as in BRCA1/2-related hereditary breast cancer compared to other types of hereditary breast cancer." (PMID 33540843, 2021). "With the attempt to clearly relate the expression of BRCA1 and the peculiar subcellular localization of HIF-1α and HSP60, the BRCA1 full length was transfected in the hereditary breast cancer model." (PMID 29584711, 2018).
high altitude pulmonary edema (2 papers, 2016 to 2026). "High altitude pulmonary edema (HAPE) susceptibility is associated with EGLN1 polymorphisms, we hypothesized that HAPE-susceptible (HAPE-S, had HAPE episode in past) subjects may exhibit abnormal HIF1α levels in normoxic conditions." (PMID 27210110, 2016).
hydatidiform mole (2 papers, 2019 to 2023). A gestational trophoblastic disorder characterized by marked enlargement of the chorionic villi, hyperplasia of the villous trophoblastic cells and hydropic changes. "Mechanistically, we speculate that upregulated HIF-1α through enhanced LIGHT signaling via its receptors is involved in sFlt-1 overproduction and in the pathogenesis of PE features seen in hydatidiform mole patients." (PMID 31300808, 2019).
hyperthyroidism (2 papers, 2024 to 2025). Overactivity of the thyroid gland resulting in overproduction of thyroid hormone and increased metabolic rate. "While enhanced HIF-1α activity in hyperthyroidism can accelerate oxygen delivery to tissues, persistent elevation may promote excessive or disorganized vascular proliferation." (PMID 41158934, 2025). "Those authors suggested that erythrocytosis in hyperthyroidism may result from the activation of HIF-1α, leading to increased expression of the EPO gene." (PMID 39518858, 2024). "Thus, it seems possible that similar mechanisms (T3 → TRβ/RXRα → HLF → HIF-1α → EPO and T3 → SHH → BMP-4 → BFU-E) may lead to increased erythropoiesis in human and feline hyperthyroidism and may explain the presence of erythrocytosis observed in this disease." (PMID 39518858, 2024).
hypertriglyceridemia (2 papers, 2025). A laboratory test result indicating elevated triglyceride concentration in the blood. "In conclusion, Serpina3c regulates adipocyte function to improve hypertriglyceridemia and macrophage inflammation via the Hif1α/glycolysis pathway." (PMID 39693610, 2025). "Serpina3c overexpression, Hif1α knockdown, and glycolysis inhibition, along with alleviated adipocyte hypertrophy and decreased lipid content, collectively indicate that Serpina3c improves hypertriglyceridemia via the Hif1α/glycolysis pathway." (PMID 39693610, 2025).
hyperuricemia (2 papers, 2024 to 2026). An abnormally high level of uric acid. "This indicates that inhibiting HIF‐1α might help mitigate inflammation and cellular damage caused by hyperuricemia." (PMID 41561638, 2026). "In hyperuricemia, the reduction in HIF‐1α may lead to abnormalities in these physiological processes, thereby affecting cardiovascular health." (PMID 41561638, 2026). "This suggests that in the context of hyperuricemia, characterized by oxidative stress and metabolic abnormalities, the stability and activity of HIF‐1α may be compromised." (PMID 41561638, 2026). "Additionally, MAP2K1 regulates the HIF‐1α signaling pathway, while hyperuricemia activates the ERK pathway, further impacting HIF‐1α." (PMID 41561638, 2026).
insomnia (2 papers, 2023 to 2025). A sleep disorder characterized by difficulty in falling asleep and/or remaining asleep. "This study confirmed that the serum levels of HIF-1α in patients with insomnia were significantly higher than those in non-insomnia patients, indicating that insomnia increased the risk of oxidative stress in AIS." (PMID 37924679, 2023). "It is not clear whether insomnia, like OSA, causes ROS/HIF-1α pathway activation, increasing oxidative stress and inflammation." (PMID 37924679, 2023).
interstitial cystitis (2 papers, 2021 to 2024). A rare chronic debilitating urogenital disease characterized by urinary frequency, urgency, and pelvic pain. "Also, an increased expression of HIF-1α, HIF-2α and VEGF-A has been shown in bladder obstruction, overactive bladder syndrome and interstitial cystitis." (PMID 33146980, 2021).
Kidney Cyst (2 papers, 2017 to 2026). Abnormal fluid filled sac within the kidney, either acquired or congenital. "Here, we demonstrate that the ATP-release channel Pannexin-1 is regulated by HIF-1α in kidney tubular cells, leading to its prominent localization at the apical membrane of kidney cysts in both human and murine ADPKD kidney tissue." (PMID 42117913, 2026).
left ventricular hypertrophy (2 papers, 2008 to 2023). Enlargement of the LEFT VENTRICLE of the heart. "At the molecular level, it appears that hypoxia-induced HIF-2α and VEGFR-2 expression are reduced in left ventricular hypertrophy, and that these are necessary, with or without the participation of HIF-1α, to promote angiogenesis in response to hypoxia." (PMID 19112498, 2008).
Leigh syndrome (2 papers, 2012 to 2023). A progressive neurological disease defined by specific neuropathological features associating brainstem and basal ganglia lesions. "This study also found that hypoxia-inducible factor 1-alpha (HIF-1α) levels were not uniform throughout the retinal layers and controlled hypoxia of the entire circulatory system may result in more uniform levels and possibly positive effects on disease progression, as seen in Leigh Syndrome." (PMID 37601627, 2023).
leishmaniasis (2 papers, 2017 to 2018). Infectious disease that is transmitted through the bite of hematophagous female phlebotomine sand flies. "Because monocytes contribute to parasite clearance in other models of leishmaniasis, we first compared the recruitment of monocytes to the spleen in Hifflox/flox–Cd11c-Cre+ mice (HIF-1α-deficient) and their Cre- littermates (HIF-1α-sufficient) at various time points of infection." (PMID 28892492, 2017).
low grade glioma (2 papers, 2025). A grade I or grade II glioma arising from the central nervous system. "A similar pattern of HIF-1α upregulation was observed in clinical samples of low-grade glioma (LGG) and GBM tumors compared to normal brain tissue, further validating the relevance of the spheroid model." (PMID 41323785, 2025). "Other relevant pathways in cancer, such as focal adhesion, cytoskeleton regulation, and chemokine signalling (VCL, THBS1-4, FLNA, LAMA2/4/5, HSPG2), might also be influenced indirectly by changes in the WWOX/HIF1A ratio, potentially impacting the overall prognosis of low-grade glioma patients." (PMID 41007296, 2025).
lymphedema (2 papers, 2021 to 2022). Excess fluid collection in tissues, causing swelling. "LEC HIF-1α deletion transiently aggravates edema in a mouse-tail lymphedema model, corroborating a critical role of LEC HIF-1α in lymphatic regeneration immediately post-surgery." (PMID 35450048, 2022). "Lymph stasis and inflammation stabilize HIF-1α in mouse lymphedema, and this high tissue HIF-1α expression is required for reparative lymphangiogenesis and wound healing." (PMID 35450048, 2022). "Enhanced lymphendothelial expression of Hif1α in clinical lymphedema and important functions for both Hif1α and Hif2α during lymphatic vascular development and regeneration in mice have been found." (PMID 33923324, 2021). "Therefore, increased HIF-1α expression with concomitant HIF-2α reduction in LECs may exacerbate lymphatic malfunctioning by promoting non-productive lymphangiogenesis and LEC phenotypic transition in chronic stage lymphedema." (PMID 35450048, 2022).
malignant peripheral nerve sheath tumor (2 papers, 2020 to 2023). Malignant peripheral nerve sheath tumor (MPNST) is a rare and often aggressive soft tissue sarcoma occurring in a wide range of anatomical sites. "The nuclear accumulation of HIF-1α was shown in malignant peripheral nerve sheath tumor (MPNST) samples." (PMID 37296922, 2023).
memory impairment (2 papers, 2015 to 2021). "Crocin treatment improved memory impairment and attenuated the gene expression of HIF‐1α and BACE1 in the brains of neonate rat." (PMID 33586916, 2021). "It was observed that the hypoxia-induced memory impairment in mice is related with enhanced expression of Hif-1α, which could have affected the levels of the antioxidative stress enzymes such as SOD and CAT." (PMID 26413121, 2015).
meningitis (2 papers, 2020 to 2024). A disorder characterized by acute inflammation of the meninges of the brain and/or spinal cord. "We therefore hypothesized a critical role of the HIF-1α/VEGF signaling in the migration of S. pneumoniae across the BBB subsequently causing meningitis." (PMID 32529267, 2020). "Based on the in vitro data and RNAseq analysis that indicated a crucial role of HIF-1α pathway at the BBB in meningitis, we targeted the HIF-1α pathway for therapeutic rescue in a murine model of pneumococcal infection." (PMID 32529267, 2020). "All these data demonstrate HIF-1α activation in both inflammatory and resident CNS cells upon meningitis in mice and humans." (PMID 32529267, 2020). "Regulation of angiogenesis and cancer-related pathways at the BBB in meningitis as indicated by bioinformatics analysis of our RNA sequencing data further support the role of HIF-1α/VEGF in meningitis similar to their role in cancer progression." (PMID 32529267, 2020). "HIF-1α activation is a general phenomenon upon infections, and elevated VEGF levels known to be regulated via HIF-1α were found in CSF of meningitis patients." (PMID 32529267, 2020). "Activation of HIF-1α was also observed in other cases of mouse and human meningitis resulting from infections with bacteria (E. coli, Cryptococcus neoformans, Mycobacterium tuberculosis), fungi and protozoa (Toxoplasma gondii) (online resource)." (PMID 32529267, 2020). "In human, murine meningitis brain samples, HIF-1α activation was observed by immunohistochemistry." (PMID 32529267, 2020). "Inhibition and knock-down of HIF-1α resulted in rescue of permeability and bacterial transmigration post-infection, thus demonstrating a critical role for HIF-1α/VEGF in bacterial transmigration and permeability at the BBB in meningitis." (PMID 32529267, 2020). "As our data argue for an involvement of HIF-1α/VEGF from both in vitro infection experiments and from immunohistochemical analysis of meningitis samples, we elaborated HIF-1α/VEGF expression in vivo at the BBB." (PMID 32529267, 2020). "To investigate the role of HIF-1α/VEGF pathway in migration of S. pneumoniae across the BBB, we analyzed mouse and human meningitis specimen for HIF-1α activation." (PMID 32529267, 2020). "Further analysis indicated a significant upregulation of HIF-1α and VEGF and these findings were supported by bioinformatics pathway analyses, showing increased HIF-1α/VEGF signaling at the BBB in meningitis." (PMID 32529267, 2020). "The overexpression of HIF-1α as a sign of hypoxia is widely observed in meningitis samples, even in areas without necrosis, indicating wider-spread penumbral conditions." (PMID 38922127, 2024). "Given the established role of HIF-1α/VEGF signaling in endothelial permeability, we hypothesized a critical role for this pathway in the BBB permeability and bacterial transmigration in meningitis." (PMID 32529267, 2020).
mesenchymal tumors (2 papers, 2016 to 2018). "Immunohistochemical studies in phosphaturic mesenchymal tumors resected from patients with documented TIO showed that HIF-1α and FGF23 were co-localized in spindle-shaped cells adjacent to blood vessels." (PMID 27468359, 2016). "Such an EGFR-specific treatment option was performed in a phase II trial for patients with synovial sarcomas and could be considered for other mesenchymal tumors that express HIF-1α." (PMID 30513863, 2018).
Metabolic (2 papers, 2023 to 2025). "In summary, HIF-1α protected against IVDD, possibly through reducing ROS production in the mitochondria and consequent inhibition of inflammation, metabolism disorders and apoptosis of NP cells, which provided a new idea for exploring the therapeutic strategies and targeted drugs for IVDD." (PMID 36064808, 2023).
microcephaly (2 papers, 2020 to 2022). A congenital or acquired developmental disorder in which the circumference of the head is smaller than normal for the person's age and sex. "Notably, heterozygous ablation of Hif1α using Emx1-Cre driver causes precocious neurogenic differentiation of neural progenitor cells, resulting in mild microcephaly." (PMID 35361248, 2022). "According to the DECIPHER database, deletion of HIF1A resulted in congenital developmental defects, including microcephaly, aplasia of the tongue, and facial asymmetry." (PMID 32766242, 2020).
Miscarriage (2 papers, 2023 to 2025). A pregnancy that ends at a stage in which the fetus is incapable of surviving on its own, defined as the spontaneous loss of a fetus before the 22th week of pregnancy. "LA enhances inducible nitric oxide synthase (INOS) expression in a HIF-1α-dependent manner, which in turn promotes M1 polarization of decidual macrophages, leading to the disruption of immune tolerance to trigger miscarriages." (PMID 37355665, 2023). "In addition, another study showed that genetic defects in epithelial membrane protein 2 (EMP2) can inhibit angiogenesis and oxidative phosphorylation by suppressing FAK and Src to inhibit the production of HIF-1α in the trophectoderm, leading to miscarriage." (PMID 37355665, 2023).
Mm (2 papers, 2013 to 2024). "This early priming of neutrophils could be blocked using iNOS inhibition, confirming that the reduced susceptibility to Mm infection due to Hif-1α stabilization is dependent on iNOS activity." (PMID 24367256, 2013). "This macrophage-specific upregulation of phd3:GFP expression by Mm infection was blocked by injection of RNA for dominant negative (DN) hif-1αb, indicating this is a Hif-1α dependent host response to Mm infection." (PMID 24367256, 2013). "Stabilization of host Hif-1α, both pharmacologically and genetically, at early stages of Mm infection was able to reduce the bacterial burden of infected larvae." (PMID 24367256, 2013). "This is consistent with stabilized Hif-1α aiding the host to combat Mm infection." (PMID 24367256, 2013).
morbid obesity (2 papers, 2010 to 2021). An excess of body weight, normally defined as an individual with a body mass index greater than 35 or a body weight greater than one hundred percent of ideal body weight. "Regarding MSR1, we found a higher expression in patients with morbid obesity, an increase in hypoxia and a positive correlation with HIF-1α." (PMID 34829944, 2021). "In this study, we found that visceral mature adipocytes from patients with morbid obesity had increased expression of HIF-1α, inflammation markers and different SRs." (PMID 34829944, 2021). "In a previous study, we found that patients with morbid obesity had high VAT HIF-1α expression." (PMID 34829944, 2021).
muscle disorders (2 papers, 2021 to 2024). "Current studies seem to point toward HIF-1α as a potential therapeutic target for muscle disorders." (PMID 34281273, 2021). "For chronic treatment of muscle disorders, the negative effect of indirect HIF1α inhibitors on protein synthesis should be avoided given the risk of exacerbating muscle atrophy." (PMID 38542301, 2024).
muscular dystrophies (2 papers, 2021 to 2023). "The role of HIF1α in pathological conditions has also been highlighted, notably in the context of muscular dystrophies." (PMID 38104132, 2023).
ocular hypertension (2 papers, 2021 to 2024). Abnormally high intraocular pressure. "Our previous work documented that Hif-1α activation after ocular hypertension led to significant increases in GLUT-1 in retinas." (PMID 39061946, 2024).
ocular tumors (2 papers, 2025). "Secondly, there is growing interest in targeting metabolic signaling pathways, including PI3K/AKT/mTOR, AMPK, and HIF-1α, as a therapeutic approach to disrupt the metabolic dependencies of ocular tumors." (PMID 40994549, 2025).